CD3E (CD3 epsilon subunit of T-cell receptor complex)
Diseases named in the same sentence as CD3E in open-access papers (continued):
Sharing a sentence is not in itself a finding about the gene and the disease.
tumor (continued). "Analysis of bulk tumor gene expression data from TCGA revealed a significant negative correlation between the genes encoding OTUB2 and intratumoral T-cell abundance (CD3E and CD8A) in multiple cancer types." (PMID 38167274, 2024). "In the TME, CD8+ (CD8a+CD8b+) T cells are known to be differentiated from lymphocyte T cells (CD45+, CD3e+), and that has a key role in anti-tumor immunity." (PMID 39682244, 2024). "Solid tumors rarely contain naive T cells, so ex vivo tumor-infiltrating T cells were stimulated with low-level CD3ε for 18 hours." (PMID 38502228, 2024). "MHC class I presentation was positively correlated with the proportion of CD45+CD3e+ cells and negatively correlated with the tumor growth rate." (PMID 39682244, 2024). "Then we used Loupe Browser 7.0 to group spots with gene characteristics (log2 count > 0) of CD68 or CD4 with CTLA4 as THC, and spots with gene characteristics of CD3D or CD3E or CD3G as tumor immune cells." (PMID 39499374, 2024). "Most bispecific antibodies that target immune cells act by binding the CD3ε subunit of T cells and a tumor cell antigen to form a cytolytic synapse." (PMID 39091493, 2024). "Multiple immune-associated genes such as CD79A, CD3E, CD3D, ZAP70, CXCR6, and GZMA were upregulated in hot tumor regions." (PMID 38803565, 2024). "Next, to detect the correlation between MHC class I expression on the cell surface and the proportion of CD45+CD3e+ cells or tumor growth rate (tumor volume on day 8/tumor volume on day 1), we performed Pearson correlation statistics." (PMID 39682244, 2024). "On the one hand, reduced tonic signaling and increased anti-tumor efficacy was achieved by introducing the RK motif of CD3ε into a second-generation FDA-approved 19BBζ CAR." (PMID 38779683, 2024). "MHC class I presentation was positively correlated with the proportion of CD45+CD3e+ cells and negatively correlated with tumor growth rate (p = 0.0159 and p = 0.0025, respectively)." (PMID 39682244, 2024). "We noted a significant decrease in tumor-infiltrating CD3e+ T cells (P = .03), CD8a+ T cells (P = .03), and PD-1+ cells (P = .03) in post-ICI samples, compared with pre-ICI samples." (PMID 38207230, 2024). "For generic T cell interaction, splenic T cells from tumor-naïve mice were activated with plate-bound anti-Cd3e/Cd28-antibodies (Tp cells) to serve as controls for tumor-antigen dependent T cell responses." (PMID 38654067, 2024). "In this experiment, 86% to 94% of differentiated GFP+ cells were positive for Lyve-1, Ter-119 and CD3e immediately prior to transfer, but only 10% of tumor-residing GFP+ cells displayed this profile 4 weeks after transfer." (PMID 38640116, 2024). "The ITPRIPL1-CD3ε axis formed by the binding of ITPRIPL1 as a ligand on the surface of tumor cells with CD3ε can inhibit TCR-CD3 complexes signal transmission." (PMID 39342365, 2024). "By employing the MCODE plugin in Cytoscape, we identified key sub-networks within the PPI network, which included genes such as IL-10, CD3E, MET, and others that were associated with anti-tumor immune response." (PMID 38327746, 2024). "Current antibody drugs targeting CD3 usually recognize CD3E and activate T cells to kill the tumor cells." (PMID 38355782, 2024). "The MoA of cibisatamab is based on the simultaneous binding of cibisatamab to CEA/CEACAM5 on tumor cells and to the CD3ε chain on T cells, which results in T-cell activation and subsequent tumor cell killing." (PMID 38881900, 2024). "Here we further identify that Ccdc134 deficiency accelerates TCR downmodulation by ubiquitinating CD3ε and its downstream pathways following TCR activation, rendering mice refractory to T cell-mediated inflammatory and anti-tumor responses." (PMID 37234153, 2023). "Specifically, we observed direct changes in the tumor microenvironment after using a ferroptosis inducer in this tumor subtype with the recruitment of CD3e+, CD4+, CD8+, and CD86+ cells, and a reduced number of CD206+ cells." (PMID 36861444, 2023).
tumor (continued). "In this aggressive and fast‐growing tumor model, CD19/CD3ε FP T cells delayed tumor growth and mice showed significant survival advantage compared to NT T cell and CD19 CAR‐T cell treated mice." (PMID 38023726, 2023). "BiTE can simultaneously engage CD3ε on T cells and tumor antigen on cancer cells, thus exerting an effective antitumor effect." (PMID 36403209, 2023). "Simultaneous binding of NILK-2301 to CEACAM5-positive tumor cells and CD3ε-expressing T-cells leads to T-cell activation, proliferation, and secretion of cytokines and cytotoxic enzymes, ultimately leading to tumor cell killing." (PMID 38087365, 2023). "Synthetic T cell receptor fusion construct (TRuC) represent a novel receptor class which consist of a tumor antigen-specific single chain variable fragment (scFv) fused to the CD3ε subunit." (PMID 36409438, 2023). "TAG72/CD3ε, δ and γ FP T cells were subsequently tested for their ability to kill tumor cells in vitro." (PMID 38023726, 2023). "TCEs, also referred to bispecific T cell engagers (BiTEs), are designed bsAbs co-targeting CD3ε and specific tumor antigens to redirect cytotoxic T cells against tumor cells." (PMID 37332039, 2023). "In summary, compared to NT T cells, CD3ε FP T cells demonstrated anti‐tumor activity in two different in vivo tumor models." (PMID 38023726, 2023). "MC38-OVA tumor cells were subcutaneously injected into Cd3e−/− mice, and after 5 days, either control or Afap1l2-edited OT-I T cells were adoptively transferred." (PMID 37388918, 2023). "The anti‐tumor activity of subsequently administered TAG‐72/CD3ε FP T cells was compared to NT T cells and TAG‐72 CAR‐T cells." (PMID 38023726, 2023). "Having demonstrated the anti‐tumor activity of FP T cells in vitro, we subsequently assessed the potential efficacy of CD3ε FP T cells in vivo." (PMID 38023726, 2023). "Immunohistochemically, tumor cells from all cases were positive for CD3ε and EBER, and 98.8% of cases were positive for the cytotoxic marker T‐cell intracellular antigen‐1/granzyme B. Positive CD56 immunostaining was observed in 72.8% (59/81) of cases." (PMID 36114786, 2023). "Here, we optimized the method of nonviral, CRISPR/Cas9 genome editing using large donor DNA delivery, knocked‐in an anti‐tumor single chain variable fragment (scFv) into the N‐terminus of CD3ε and efficiently generated fusion protein (FP) T cells." (PMID 38023726, 2023). "The secreted PD‐L1/CD3ε Nb‐BiTE can not only redirect Nb‐CAR‐γδT but also recruit un‐transduced bystander T cells against tumor cells expressing PD‐L1, thereby enhancing the activity of Nb‐CAR‐γδT therapy." (PMID 37078788, 2023). "Bispecific T‐cell engager (BiTE) is an artificial bispecific antibody construct that simultaneously binds a surface antigen on tumor cells and a surface molecule (i.e., CD3ε) on T cells." (PMID 37078788, 2023). "CD19/CD3ε FP T cells killed CD19hi tumor cells (HeLa cells expressing CD19) as efficiently as the CD19 CAR‐T cells." (PMID 38023726, 2023). "TRuC-T cells consist of a tumor antigen binding domain fused to the CD3ε subunit of the TCR complex, which upon its integration into the TCR redirects T cell killing against tumor cells." (PMID 37848682, 2023). "Despite the differences between the ICDs of CD3ε and ζ, BBε and BBζ CARs revealed very similar responses and gene profiling after stimulation with tumor cells." (PMID 37932456, 2023). "We found that TMEM41A overexpression was correlated with EC stromal, immune, and estimate scores and was linked with tumor purity, immune cells (such as the macrophages, CD8 T cells, and TFH), and immune cell markers (such as the CD8A, CD3D, and CD3E)." (PMID 37478120, 2023). "They most commonly target the CD3ε subunit of the T-cell receptor (TCR) and a tumor-associated or tumor-specific antigen (TAA/TSA)." (PMID 37754534, 2023).
tumor (continued). "We therefore generated a TCRm bispecific T cell engager (TCRm-BiTE) comprising Trp2/H2-Kb TCRm scFv clone 13 and 2C11 anti-CD3e scFv27 to recruit T cells to tumor cells." (PMID 36593402, 2023). "With the aim to build a therapeutic platform against T-ALL, we developed a novel asy metric BTCE that simultaneously binds a unique epitope of CD1a and CD3ε (CD1a x CD3ε) to recruit and trigger a powerful T-cell-mediated anti-tumor response." (PMID 35740552, 2022). "In essence, the agents bind to the tumor cells and only when attached to a plasma membrane, the monovalent anti CD3ε component triggers T-cell activation through the T-cell receptor leading to tumor cell killing." (PMID 35154495, 2022). "The in vivo anti-tumor activity of CD1a x CD3ε against CD1a-expressing T-ALL cells was investigated." (PMID 35740552, 2022). "T-cell engager antibodies (TCEs) redirect cytotoxic T-cells to tumor cells by simultaneously binding to a component of the TCR complex (commonly CD3E) and a tumor associated antigen (TAA) on tumor cells." (PMID 36291540, 2022). "Consistently with these in vitro data, CD1a x CD3ε led to a significant anti-tumor activity and survival advantage of treated animals in a mouse model of human T-ALL reconstituted with human immune effectors." (PMID 35740552, 2022). "The EpCAM BiTE secreted from infected malignants effectively mediated the binding of EpCAM-positive tumor cells and CD3ε on T cells, which led to activation of naive T-cell and the release of cytokines, such as IFN-γ and IL-2." (PMID 36451817, 2022). "The early therapeutics BsAbs were T cell engagers, and their effects were first demonstrated in the mid-1980s.104,105 BiTEs are capable of binding CD3ε within the TCR complex and a selected tumor-associated antigen (TAA) on tumor cells simultaneously." (PMID 35132063, 2022). "Bispecific antibodies binding a surface tumor antigen and CD3ε induce tumor redirected T cell killing." (PMID 35154495, 2022). "BiTE molecules consist of two distinct single-chain variable fragments (scFvs) that can recognize antigens on tumor cells and CD3ε on T cells, respectively." (PMID 36230871, 2022). "Meanwhile, combining the extracellular domain of CD3ε and BiTE conferred a tumor-specific role on T cells, which function similar to CAR-T cells." (PMID 36230871, 2022). "In our Western blot and CCK8 experiments, we found that the higher the expression of CD3E represented the higher the invasion of tumor cells." (PMID 34557404, 2021). "CD3/CD28 Dynabeads and an EpCAM BiTE, which targets EpCAM on tumor cells and CD3ε on T cells, were included as positive controls for activation-induced cell death (AICD) and BiTE-induced T cell death." (PMID 33820820, 2021). "Since CD2, CD3D, CD3E, and CXCR6 predict very favorable prognosis in CSCC, we evaluated the association of this new signature at transcriptomic level with the presence of tumor-infiltrating immune cell populations in CSCC." (PMID 34692491, 2021). "We considered that CD3E plays an active role in most TMEs and passed It binds to T cell surface receptors in the form of a complex to regulate T cell-mediated anti-tumor immune evasion." (PMID 34557404, 2021). "GBM stood out as having the highest CD163/CD3E ratio of the 30 tumor types analyzed, indicating GBM tumors have a uniquely TAM-dominated TIME combined with poor T cell infiltration." (PMID 34083417, 2021). "The coexpression hub genes of PD-1 are related to immunity, in which CD3E is a prognostic marker that is involved in the PD-1/PD-L1-induced tumor immune escape." (PMID 34124265, 2021). "To further explore the mechanism by which CD3E promotes tumor immune evasion in brain tissue and LGG, we performed complex bioinformatics work including functional enrichment and GSEA analyses." (PMID 34557404, 2021). "Next, we aimed to investigate predictive role of CD3E expression in predicting responses to immune checkpoint inhibitors of LGG using Tumor Immune Dysfunction and Exclusion (TIDE) algorithm." (PMID 34557404, 2021).
tumor (continued). "In subsequent experiments, we found that the higher the expression of CD3E in tumor cells, the stronger the invasion ability of LGG." (PMID 34557404, 2021). "Alteration of CD3-ε, which is involved in tumor-induced T-cell apoptosis, leads to tumor induced caspase-dependent apoptosis in high proportion of tumor infiltrating T-lymphocytes." (PMID 33673332, 2021). "The second is that this experiment lacks research on the expression of CD3E in different cell populations in tumor samples." (PMID 34557404, 2021). "Bispecific T cell engagers (BiTEs) can indiscriminately endow T cells with tumor-targeting ability by binding CD3ε that fully mobilize T cells to kill tumors." (PMID 34356854, 2021). "Bispecific T cell engagers (BiTEs) are immunostimulatory bispecific antibodies, consisting of an anti-CD3ε scFv fused to a tumor-targeted antibody via a flexible linker that primarily activates T cells to kill tumor cells." (PMID 34578321, 2021). "Using lymphocyte markers, we confirmed the enrichment of T cells (Cd3e) (2-8 fold) and B cells (~4 fold) in TILs relative to tumor tissues." (PMID 32244522, 2020). "We found T cells positive for the CAR and mouse-CD3e confirming the presence of CAR T cells in tumor xenografts." (PMID 32033208, 2020). "T cells (expressing Cd2, Cd3e, Cd3g, and Cd6) were the most abundant immune cell type in tumor tissues, followed by cytotoxic cells (expressing Gzma and Klrd1)." (PMID 32612611, 2020). "Ex vivo tumor analysis on day 33 indicated a low but significant intratumoral CD3ε+ EGFRt+ CAR-T cell population in EC17-treated animals which amounted to ~1% total viable digested tumor-derived cells (right bar graph)." (PMID 30941303, 2019). "Accordingly, we used mRNA expression of the pan T-cell marker CD3E as a metric for T-cell abundance within a tumor, and examined correlations between expression of CD3E and putative targets across 9,601 human tumors spanning 31 cancer types." (PMID 31360302, 2019). "We examined a 40-gene panel of candidate immune regulators and an unbiased list of 12,082 expressed genes in cancer to find genes consistently co-expressed with the T-cell marker CD3E in the tumor microenvironment." (PMID 31360302, 2019). "Consistent with the OS data, the lowest quartile of PDA patients had greater transcriptional expression of cd3e and cd8a, suggesting the presence of more cytotoxic T cells in the tumor." (PMID 30926808, 2019). "In an unpublished study carried out at Janssen R&D, several versions of a bispecific antibody (CD3ε arm)/centyrin (tumor antigen arm) combination were made and tested in vitro for tumor cell killing activity." (PMID 31544847, 2019). "This TRBA consisted of a Fab arm binding to CD3ε on one side and two domain antibodies binding the tumor antigen in place of the other Fab arm." (PMID 31544847, 2019). "The position of the tumor antigen binding arm on the molecule, that is, the geometry/distance of binding between the CD3ε arm and the tumor antigen arm, made a ca. 100-fold difference in in vitro killing activity." (PMID 31544847, 2019). "We deemed genes whose expression is highly correlated with CD3E—and therefore are likely to be expressed in T cells within the tumor microenvironment—to be promising targets for therapy." (PMID 31360302, 2019). "In accordance with IFNγ release, EC17 also triggered CAR-T cell expansion identified as human CD3ε+ EGFRt+ events in mouse blood, and cells persisted up to 54 days in tumor-bearing animals (last measurement)." (PMID 30941303, 2019). "Utilizing their TruC platform, the tumor specific binding scFv is fused to the extracellular domain of CD3ε, allowing for complex activation upon scFv-target binding, bypassing TCRα/β-MHC interactions." (PMID 31544847, 2019). "BiTEs are bi-specific soluble antibodies targeting a tumour antigen on one arm and CD3ε on the other arm, resulting in an antibody that is capable of engaging T cell cytotoxicity of the tumour." (PMID 31892219, 2019).
tumor (continued). "We have previously shown that the tumor killing activity of γδ T cells can be increased by addition of the anti-CD3ε antibody UCHT1." (PMID 30038626, 2018). "In its application to MM, the method involves the construction of a recombinant antibody to two different epitopes – the CD3ε molecules on tumor-specific T cells and a tumor-specific receptor on the myeloma cell." (PMID 30544512, 2018). "Despite this, dsTCRs assemble with CD3 chains with proper juxtaposition of CD3ε chains, express on the cell surface, and mediate functional, antigen-specific responses, including tumor cell killing." (PMID 27823582, 2016). "Through global transcriptome analysis, immune-related functions were found to be key regulators in the spleen associated with tumor progression as a function of age with CD2, CD3ε, CCL19, and CCL5 being the key molecules involved." (PMID 26497558, 2015). "We found that CD8 T cells which had infiltrated MCA-205-OVA tumors had significantly lower surface CD3ε than CD8 T cells from the spleen of MCA-205-OVA tumor bearing mice, a finding that is consistent with high arginase-1 activity." (PMID 24614600, 2014). "The tumor cells were positive for CD3ε in 11 cases (11/13, 84.6 %) and positive for CD2 in 6 cases (6/13, 46.2 %)." (PMID 24952511, 2014). "In the second component, CGS 2 (C1QB), CGS 19 (GZMB), CGS 31 (CD8A) and CGS 34 (CD3E) correlated (R2>0.25) with the tumor cell content or its counterpart, i.e., the amount and function of bystander cells." (PMID 24223701, 2013). "Univariate survival analyses using median cutpoints for immune cell markers revealed that patients with low CD3ε mRNA levels in their tumor biopsies had significantly shorter tumor-free time periods (p = 0.03)." (PMID 21980389, 2011). "Our study demonstrated an association between CD3ε, CD25, CD68, and ICAM-1 mRNA levels in BCC tumor biopsies and the risk for subsequent tumors." (PMID 21980389, 2011). "Host immunity developed against MSI cancer cells was appreciated by quantifying the number of CD3ε-positive tumor-infiltrating lymphocytes (TILs)." (PMID 18612427, 2008). "Notably, the CD3ε-Nb EVs exhibited minimal immunogenicity risks compared to lipid-based and lentiviral carriers, despite their comparable anti-tumor activity." (PMID 41632088, 2026). "Thus, H28E CAR-T cells outperform their conventional counterpart in tumor suppression, which is largely attributed to the unique property of the intracellular signaling module of CD3ε." (PMID 39809749, 2025). "In GBM, EGFRvIII confers tumor specificity, whereas CD3ε provides T-cell cytolytic potential." (PMID 41209565, 2025). "It functions by binding to CD20 expressed on the surface of target B cells and the CD3ε chain (CD3ε) on effector T cells, thereby inducing T cell activation, proliferation, cytokine release, and tumor cell lysis, providing a new treatment option for R/R DLBCL patients." (PMID 40691459, 2025). "Together, B7-H3 and CD3ε delineate an inhibitory-activating axis that provides a clear rationale for BsAbs co-targeting both to relieve immunosuppression, reinvigorate T cells, and promote tumor clearance." (PMID 41209565, 2025). "Additionally, OBP-801 intervention is accompanied by increased MHC class I molecule expression and a rise in the proportion of CD45+CD3e+ T cells among tumor-infiltrating lymphocytes." (PMID 40573881, 2025). "Simultaneous binding of cibisatamab to CEA and CD3ε causes T-cell activation independent of T-cell receptor specificity, leading to lymphocyte-mediated tumour cell killing, immune-stimulatory cytokine release and further release of tumour antigens." (PMID 38750034, 2024). "Furthermore, in the RENCA allograft mouse model, combination treatment significantly increased LMP2 expression, MHC class I expression on the cell surface, and the percentage of CD45+ CD3e+ T cells and reduced tumor volume." (PMID 39682244, 2024).